GFAP (glial fibrillary acidic protein)
Diseases named in the same sentence as GFAP in open-access papers (continued):
Sharing a sentence is not in itself a finding about the gene and the disease.
Cerebral ischemia (continued). "Twenty-four hours after cerebral ischemia induction, a dramatic increase in GFAP immunoreactivity was observed in the peri-infarct penumbra cortex in Poldip2+/+ mice." (PMID 29452577, 2018). "GFAP-knockout mice exhibit larger lesions and a greater reduction in cerebral blood flow following focal cerebral ischemia." (PMID 27379176, 2016). "Cerebral ischemia triggers reactive astrogliosis, a condition characterized by an increase of GFAP levels in astrocytes." (PMID 26858637, 2016). "In our preclinical findings, protein analysis showed that both BDNF and GFAP levels were downregulated by cerebral ischemia while a local and sustained increase in their expression in the perilesioned tissue followed oral administration of co-ultraPEALut." (PMID 26706245, 2016). "The PACAP38 was strongly coexpressed with Neu-N, GFAP, and vWF in ischemic areas, suggesting brain ischemia upregulated PACAP38 in neurons, glia, and endothelial cells." (PMID 25523790, 2015). "Following cerebral ischemia, GFAP-signals were markedly stronger in female transgenic mice than in males." (PMID 25147799, 2014). "Immunostaining for OX-42 and GFAP was used to assess the pathological changes of microglia and astrocytes, respectively, which are involved in the neuroinflammatory processes after cerebral ischemia-reperfusion." (PMID 23437066, 2013). "Nevertheless, GFAP−/− mice have been demonstrated to be more sensitive to spinal cord injury, to cerebral ischemia, and to neurotoxicity, indicating a protective role of GFAP." (PMID 22912745, 2012). "Double fluorescence analysis revealed colocalizations of IL-6 with GFAP and NeuN within the ipsilateral cerebral cortex and infarcted core indicating that IL-6 is particularly expressed by astrocytes and neurons after cerebral ischemia." (PMID 22031820, 2011). "Moreover, brain ischemia is followed by the astrocyte activation (reactive gliosis) characterized by increased glial fibrillary acidic protein (GFAP) expression, among others." (PMID 40804606, 2025). "Our results imply that exercise alters GFAP expression after cerebral ischemia." (PMID 36880055, 2023). "After cerebral ischemia occurs, astrocytes undergo changes, such as cell body enlargement, cell swelling, increased protrusions, and proliferation, and the expression of the specific marker GFAP for astrocytes also increases." (PMID 36982280, 2023). "Glial cells, such as GFAP, are significantly affected by cerebral ischemia." (PMID 36151103, 2022). "In addition, NSP was also shown to play an important role in cerebral ischemia, while GFAP was proposed as a sensitive biomarker for the differentiation of ischemic and haemorrhagic stroke." (PMID 34300256, 2021). "Usnic acid not only could reduce activation rate of caspase-3 as a key apoptosis mediator in the CA1 pyramidal cells but also decrease the number of Iba-1 and GFAP-positive cells as neuroinflammation factors after cerebral ischemia." (PMID 32963745, 2020). "Moreover, the results of immunofluorescence staining showed a significant decrease in the expression of GFAP(+)/AQP4(+) cells after cerebral ischemia following EA preconditioning." (PMID 26952102, 2016). "Thus an upregulation of GFAP and vimentin suggests that structure and/or function of the retina has been compromised after 15 minutes of global cerebral ischemia." (PMID 27322388, 2016). "Increased expression of GFAP represents astroglial activation during cerebral ischemia." (PMID 27548129, 2016). "After brain ischemia, astrocytes are activated resulting in increased production of intermediate filament proteins, such as vimentin and GFAP, and a phenomenon termed reactive astrogliosis occurs, which is characterized by profound morphological and functional changes in astrocytes." (PMID 26690124, 2015). "We showed that ADEV GFAP may reflect dynamic changes in the first month following brain ischemia." (PMID 38891912, 2024).
Cerebral ischemia (continued). "In support of this contention, previous work by others has demonstrated that GFAP/vimentin knockout mice exhibit reduced reactive astrogliosis and significantly enhanced neuronal damage following a cerebral ischemia, suggesting that reactive astrogliosis is neuroprotective after a cerebral ischemia." (PMID 37106821, 2023). "In addition, utilizing the FBN-ARO-KO and GFAP-ARO-KO mice in disorders other than global cerebral ischemia could also help to further delineate the role of ADE2 and NDE2 in various aspects of these other neurological disorders." (PMID 36552208, 2022). "Immunofluorescence staining showed that GFAP-immunoreactive cells in the peri-infarct area of ipsilateral cortex and striatum that exhibited the typical features of reactive astrocytes underwent progressively an augmentation in number 6 h and 24 h after cerebral ischemia." (PMID 31167655, 2019). "Next, we performed co‐localization analysis of AIM2 with NeuN (a neuronal marker), GFAP (an astrocyte marker), Iba1 (a microglial marker), and CD31 (an endothelial cell marker) in the penumbral area at days 7 and 14 after cerebral ischemia." (PMID 39854137, 2025). "EE decreased the number of BrdU+/GFAP+ cells (10.2 ± 1.9/HPF, P < 0.01) around the infarcted area after cerebral ischemia." (PMID 37688770, 2023). "After cerebral ischemia, the expressions of AQP-4 and GFAP are upregulated, and the foot processes of astrocytes swell." (PMID 34975411, 2021). "The observed increase in immunoreactivity of the penumbra tissue to the glial marker GFAP at 4 and 24 h after PTS indicates the early activation of astrocytes after cerebral ischemia." (PMID 31200484, 2019). "To investigate the microscopic structural changes of NVU, we determined the expression changes of NVU markers, including NeuN (neuronal marker), GFAP (glial cell marker), and CD34 (vascular endothelial cell maker) on the 14th day after cerebral ischemia." (PMID 27391841, 2016). "The role of the increased microglial surveillance is not known; however, evidence has shown that GFAP null mice are less resistant to spinal cord injuries and cerebral ischemia." (PMID 35406788, 2022). "Moreover, injection of netrin-1 attenuated GFAP expression (netrin-1 0.27 ± 0.06 vs. BSA 0.62 ± 0.04, p < 0.001) and the release of interleukins and reduced infarct volume after brain ischemia (netrin-1 0.27 ± 0.06 vs. BSA 0.62 ± 0.04 mm3, p < 0.05)." (PMID 30227858, 2018). "To determine whether high levels of LC3B and Beclin-1 by Hcy treatment occur in a specific population of cells after cerebral ischemia, we co-stained for LC3B (or Beclin-1) and NeuN (neuron marker) (or glial fibrillary acidic protein (GFAP, astrocyte marker))." (PMID 27455253, 2016). "The injured cortical tissues of rats with cerebral ischemia exhibited decreased protein expression of neuron-related MAP-2 and SNAP25, though there was evidence of the increased protein expression of macrophage/microglia-related CD68 and astrocyte-related GFAP." (PMID 34943061, 2021). "However, it is also possible that increased GFAP expression after cerebral ischemia is not entirely detrimental." (PMID 22920191, 2012). "Moreover, adult mice lacking GFAP [GFAP(−/−)] show attenuated reactive gliosis, reduced glial scar formation after focal brain ischemia as compared to injured developing brain where there is only an increase in the survival of newborn neurons." (PMID 22701792, 2012). "The current study demonstrated the activation of astrocytes and microglia 24 hours after cerebral ischemia and found that knocking out TMEM166 significantly inhibited the activation of TMEM119-positive microglia, but not GFAP-positive astrocytes." (PMID 37611898, 2024). "We could not detect significant changes in the level of GFAP in the hippocampus or frontal brain cortex either under the influence of insulin administration or under the influence of autophagy and apoptosis inhibitor administration in rats with brain ischemia and reperfusion." (PMID 39057034, 2024).
Cerebral ischemia (continued). "Even though astrocytes are reported to undergo necroptosis in mouse models of spinal cord injury and cerebral ischemia, we did not see any P-MLKL expression co-localize with GFAP-positive astrocytes from old mice." (PMID 34515928, 2021). "Similarly, after brain ischemia, RFP+ cells did not express cluster of differentiation 13 (CD13), neuronal nuclei (NeuN), GFAP, or ionised calcium binding adaptor molecule 1 (Iba-1)." (PMID 39106252, 2024). "GSI treatment after cerebral ischemia do not alter the total number of reactive astrocytes (GFAP+), but reduce the number of RC2+ astrocytes and the number of proliferative reactive astrocytes (GFAP+ KI67+)." (PMID 37936690, 2023).
glaucoma (78 papers, 2008 to 2025). Increased pressure in the eyeball due to obstruction of the outflow of aqueous humor. "It is still an open question if the deficiency of GFAP autoantibody is involved in dysregulated astrocyte activation during glaucoma progression." (PMID 40528237, 2025). "Overexpression of glial fibrillary acidic protein (GFAP) is linked to glaucoma pathogenesis and plays a pivotal role in astrocyte-driven neuroinflammation." (PMID 40528237, 2025). "This study aimed to assess the neuroprotective effects of a monoclonal antibody (mAb) targeting GFAP in glaucoma and to elucidate the underlying mechanisms." (PMID 40528237, 2025). "As in many neurodegenerative pathologies, dysfunctions in glaucoma mouse models are associated with reactive gliosis and microglia activation, usually measured by increases in GFAP and IBA-1 expression levels, respectively." (PMID 38337691, 2024). "In glaucoma patients as well as in rodent preclinical models of glaucoma, higher expression of glial fibrillary acidic protein (GFAP) was found to be associated with the degeneration of the optic nerve fibers." (PMID 35236378, 2022). "One of the most interesting phenotypic findings in guca1c KO animals was the upregulation of GFAP in Müller cells, and the evidence of apoptosis in some ganglion, indicating the existence of gliosis and glaucoma-like alterations associated with GCAP3 LoF." (PMID 32422965, 2020). "Glaucoma-like pathology in the D2 retina is also associated with significant astrocyte and Mueller cell reactive gliosis, which is evident by upregulation of GFAP expression." (PMID 22952717, 2012). "Retinal astrocytes exhibit indicators of reactivity – such as upregulation of GFAP and remodeling – in both human glaucoma and animal models, but the extent of their causal role in disease progression remains unknown." (PMID 37829657, 2023). "This might classify down-regulation of GFAP AABs as potential diagnostic marker for glaucoma, possibly in combination with further AAB biomarkers." (PMID 34943212, 2021). "Therefore, in rodent preclinical models of glaucoma, higher GFAP immunostaining was found to be associated with the degeneration of (optic nerve) (ON) fibers." (PMID 32106630, 2020). "GFAP-induced reactive gliosis is implicated in RGC loss following injury, making GFAP a compelling candidate target for glaucoma treatment." (PMID 40528237, 2025). "Collectively, this study demonstrates that targeting GFAP with a monoclonal antibody effectively suppresses astrogliosis and attenuates neuroinflammation in vivo, resulting in protection of RGCs in a glaucoma model." (PMID 40528237, 2025). "Previous studies have shown that natural anti-GFAP autoantibodies are down-regulated in primary open angle glaucoma patients, suggesting an impaired protective autoimmunity." (PMID 40528237, 2025). "Given the critical role of astrocyte-microglia interactions in the pathogenesis of glaucoma, we sought to clarify microglial alteration in response to GFAP mAb-inhibited astrogliosis." (PMID 40528237, 2025). "Here, we postulated a new perspective in the sense of supplementing GFAP antibody to confer neuroprotection in glaucoma." (PMID 40528237, 2025). "GFAP reached the highest levels in the glaucoma subgroups having comorbidities (POAG, NTG), probably resulting from the abundant disease-load often seen in older people." (PMID 40141267, 2025). "The findings suggest that targeting GFAP represents a promising immunotherapeutic strategy for glaucoma treatment." (PMID 40528237, 2025). "Retinal astrocytes have shown to become reactive in response to traumatic injury, hypoxia or glaucoma, modifying functions and gene expression (such as upregulating GFAP and phagocytic genes) and losing their typical arrangement to culminate towards gliosis." (PMID 41357352, 2025).
glaucoma (continued). "Future studies will incorporate extended observation periods and functional assessments, including RGC counts, GFAP quantification, and functional studies, as well as direct comparisons with established glaucoma models." (PMID 41155155, 2025). "GFAP dysregulation is recognized as an early marker for retinal injury, observed in human glaucomatous donor eyes and various experimental glaucoma models." (PMID 40528237, 2025). "Similar neuroprotective effects have been observed in glaucoma patients in several autoantibodies, such as anti-γ-synuclein and anti-GFAP." (PMID 41042282, 2025). "In this study, the GFAP mAb treatment delayed the progression of glaucoma neurodegeneration structurally and functionally." (PMID 40528237, 2025). "These efforts will be crucial for advancing GFAP mAb as a potential treatment for glaucoma and other retinal neurodegenerative diseases." (PMID 40528237, 2025). "We used a bioinformatic approach to explore the putative mechanism of GFAP mAb regulation in glaucoma signature proteins." (PMID 40528237, 2025). "More importantly, the proteins regulated by GFAP mAb formed a closely connected protein interaction network with the characteristic proteins of glaucoma, in which GFAP and Caspase-1 were revealed as the central nodes." (PMID 40528237, 2025). "Placebo-treated glaucoma rats (Bead + P) showed significantly increased GFAP levels compared to the PBS + P and Bead + H groups (p < 0.001, and p < 0.001)." (PMID 40427431, 2025). "While our findings highlight the neuroprotective potential of GFAP mAb in modulating astrocyte reactivity and neuroinflammation in glaucoma model, clinical translation will require addressing several challenges." (PMID 40528237, 2025). "When observing GFAP staining for each subject, it became apparent that there were more reactive astrocytes in glaucoma subjects than in control when observing its morphology." (PMID 39191397, 2024). "In rodent models with chronic ocular hypertension or human glaucoma eyes, GFAP expression was found to increase in the ONH, but the results vary depending on the duration of IOP elevation or location of the ONH." (PMID 38612500, 2024). "Like previous studies of experimental glaucoma, the present study detected morphological characteristics of reactive astroglia, including hypertrophy of their cellular processes with increased GFAP immunolabeling." (PMID 38824526, 2024). "Further, the ratio of overall fascicular area to GFAP positive area was significantly greater for control subjects (462.4 μm2 ± 73.66) than the same ratio for glaucoma subjects (268.0 μm2 ± 112.1, p = 0.0011, CI 95% -296.1, -92.67)." (PMID 39191397, 2024). "In this study, not only was GFAP fluorescence intensity significantly increased in glaucoma optic nerves, there was also a greater GFAP positive area indicating more active astrocytes." (PMID 39191397, 2024). "The immunoreactivities of GFAP and GS, the glial cell markers, significantly increased in Müller cells of the damaged area and inner and outer layers of the glaucoma retinas, which were markedly attenuated by treatment of ERCMs and PDGF-AB." (PMID 37175778, 2023). "In glaucoma patients, astrocytes and Müller cells react through hypertrophy and increased GFAP expression, which suggests that retinal gliosis is an important reactive mechanism in this disease." (PMID 37744880, 2023). "In the early stage of glaucoma, cell density and GFAP expression of retinal astrocytes are reduced, and the morphological remodeling of ONH astrocytes is reversible." (PMID 36466782, 2022). "Several models of glaucoma have showed that the number of astrocytes increases with increased GFAP immunoreactivity, and this was also seen on the extracellular matrix remodeling on the ONH." (PMID 35778750, 2022).